ZYX (zyxin)
Description:
Adhesion plaque protein. Binds alpha-actinin and the CRP protein. Important for targeting TES and ENA/VASP family members to focal adhesions and for the formation of actin-rich structures. May be a component of a signal transduction pathway that mediates adhesion-stimulated changes in gene expression (By similarity).
Synonyms: ESP-2; HED-2
Tractability: Antibody: its Gene Ontology location is reachable by antibodies, with high confidence. PROTAC: ubiquitination databases record sites on it; its protein half-life has been measured.
Target class: Adhesion
Gene: Protein-coding gene on chromosome 7 (143,381,295 to 143,391,111, forward strand). Ensembl gene ENSG00000159840.
Subcellular location: Cytoplasm; Cytoplasm, cytoskeleton; Nucleus; Cell junction, focal adhesion
Subcellular location (Human Protein Atlas): Focal adhesion sites; Actin filaments; Plasma membrane
Gene Ontology:
Molecular function: protein binding; RNA binding
Biological process: integrin-mediated signaling pathway; stress fiber assembly; transforming growth factor beta receptor signaling pathway; cell-cell signaling; cell-matrix adhesion; cellular response to transforming growth factor beta stimulus
Cellular component: actin cytoskeleton; adherens junction; focal adhesion; nucleus; stress fiber; cytoplasm; cytoskeleton; phagocytic vesicle
Genetic constraint (gnomAD): Loss-of-function variants: 37 observed, 56.38 expected, observed/expected ratio (o/e) 0.66, 90% interval 0.5 to 0.86. The upper end of that interval is the gene's LOEUF score, 0.86, which puts it in group 3 of 6, group 1 being the genes least tolerant of losing a copy. Missense variants: 762 observed, 766.9 expected, observed/expected ratio (o/e) 0.99, 90% interval 0.94 to 1.05. Synonymous variants: 324 observed, 316.69 expected, observed/expected ratio (o/e) 1.02, 90% interval 0.93 to 1.12.
Homologues: Orthologues: chimpanzee ZYX (99% identical), macaque ZYX (99% identical), rabbit ZYX (90% identical), mouse Zyx (87% identical), rat Zyx (87% identical), pig ZYX (84% identical), dog ZYX (74% identical), guinea pig ZYX (52% identical), tropical clawed frog zyx (48% identical), zebrafish zyx (37% identical), Caenorhabditis elegans unc-115 (16% identical). Paralogues in human: TRIP6 (32% identical).
Diseases named in the same sentence as ZYX in open-access papers:
ZYX is named in the same sentence as 82 diseases in open-access papers, as found by Europe PMC text mining. Sharing a sentence is not in itself a finding about the gene and the disease. The quoted sentences say what the papers report.
breast cancer (22 papers, 2007 to 2026). A primary or metastatic malignant neoplasm involving the breast. "In human breast cancer and colorectal cancer, zyxin deficiency reduces cancer cell proliferation and migration." (PMID 35501542, 2022). "In line with this important role of zyxin in the EMT process, zyxin has been strongly linked to several types of cancer (progression), including bladder and breast cancer and Ewing’s sarcoma, where it acts as a tumour-suppressor." (PMID 34827182, 2021). "Importantly, overexpression of Zyxin was observed within human breast cancer tissues and its expression level was associated with tumour progression and metastasis." (PMID 27030211, 2016). "In cases of breast cancer, zyxin protein levels have been found to be significantly higher in tumour tissues compared with adjacent normal breast tissue, with moderate to high expression observed in over 70% of tumour samples." (PMID 41596291, 2026). "ZYX lactylation enhances its interaction with β-catenin and promotes the epithelial–mesenchymal transition and metastasis of breast cancer cells." (PMID 40026531, 2025). "In breast cancer, approximately 70% of breast cancer tissues express zyxin, whereas normal breast tissues have an expression rate of only about 5%." (PMID 38712343, 2024). "Upon performing the STITCH/STRING analysis, we observed that zyxin interacts with BCAR1 (Breast cancer anti-estrogen resistance protein 1), which coordinates tyrosine kinase-based signaling." (PMID 33808029, 2021). "Zyxin-knockdown in MDA-MB-231 breast cancer cells abrogates the TGFβ-mediated E-cadherin downregulation and impairs TGFβ-induced cell motility, supporting the notion that zyxin controls TGFβ-induced migration." (PMID 33672325, 2021). "In contrast, high levels of Zyxin and nuclear YAP were reported in breast cancer tissues and both causes the acquisition of transformed features in breast cells." (PMID 31882643, 2019). "Zyxin is upregulated in human breast cancer and positively correlates with histological stages and metastasis." (PMID 27030211, 2016). "To further study the role of Zyxin in human cancer, we examined the expression level of Zyxin in human breast cancer tissue microarrays." (PMID 27030211, 2016). "DST serves as a candidate tumor suppressor and potential biomarker in breast cancer, maintaining focal adhesion integrity, and promoting cell spreading and cell-matrix adhesion while preventing Zyxin accumulation, stabilizing LATS, and restricting YAP activation." (PMID 40228435, 2025). "Zyxin has been shown to stimulate EMT in breast cancer by rearranging microfilaments." (PMID 35501542, 2022). "One of the rare mechanistic studies revealed that, in breast cancer cells, cytoplasmic zyxin can inhibit the HIPPO pathway, thereby promoting cell proliferation via nuclear translocation of the proliferation-associated co-transcriptional activator yes-associated protein (YAP)." (PMID 35563679, 2022). "ZYX is overexpressed in breast cancer and positively correlated with breast carcinoma metastasis." (PMID 31108958, 2019). "YAP/TAZ-TEAD-mediated expression of Receptor of Hyaluronan-Mediated Motility (RHAMM) promotes migration and invasion of mesothelioma and breast cancer cells, and Zyxin was found to promote breast cancer cell migration and invasion during YAP/TAZ-TEAD2-mediated EMT." (PMID 29642615, 2018). "Overexpression of LASP1 in breast cancer may regulate gene transcription by recruiting zyxin to focal adhesions and induce tumor cell growth and migration." (PMID 27070597, 2016). "Increased LASP1 expression could lead to a more aggressive breast carcinoma phenotype, and knocking down LASP1 may reduce the migratory capacity of breast cancer cells, possibly by influencing the localization of zyxin." (PMID 22713668, 2012). "The results demonstrate that Zyxin may be a potential prognostic marker in breast cancer patients." (PMID 27030211, 2016).
breast cancer (continued). "Increased levels of focal adhesion proteins palladin, zyxin, integrin-linked protein kinase (ILK) and the adherens junction protein nexilin, are consistent with GC-stimulated formation of adherens junctions and tight junctions, previously observed in TM cells and in mammary tumor cells." (PMID 22876128, 2012). "Despite this discrepancy, SEH1L, similar to ZYX, GJA1, and TUBA4A, was upregulated in DOX-resistant breast cancer cells in the independent transcriptomic dataset GSE76540." (PMID 41153808, 2025). "Zyxin directly influences cell spreading and proliferation by binding to the LASP-1 protein, thereby promoting the development and progression of breast cancer." (PMID 38712343, 2024). "In their study on ovarian cancer and breast cancer cell lines, they observed that altered expression of LASP-1 protein, which is a focal adhesion molecule, resulted in changes in the amount of ZYX in focal adhesions, which affected cell proliferation and migratory abilities." (PMID 35740950, 2022). "For example, the interaction of Zyxin with NOLC1 (Nucleolar and coiled-body phosphoprotein 1) and BCAR1 (Breast cancer anti-estrogen resistance protein 1) suggest a novel role of zyxin in ribosomal processing and in tyrosine kinase-based signaling, respectively." (PMID 33808029, 2021). "Similar to findings in human breast cancer, our immunofluorescence experiments have shown that absence of LASP-1 in focal contacts dramatically influences zyxin distribution." (PMID 17211471, 2007). "Interestingly, recent work has shown, that knock-down of LASP-1 in metastatic breast cancer cell lines BT-20 and MCF-7 results in a strong inhibition of proliferation and migration and leads to a reduction of zyxin at focal contacts through absence of LASP-1." (PMID 17211471, 2007).
glioblastoma (8 papers, 2009 to 2023). The most malignant astrocytic tumor (WHO grade IV). "ZYX has been reported to have an association with glioblastoma, colon cancer, and pancreatic cancer." (PMID 37190333, 2023). "Meanwhile, previous research has demonstrated that ZYX substantially increases the malignancy of glioblastoma and colon cancer while suppressing the growth of non-small-cell lung cancer in patients." (PMID 37626810, 2023). "ZYX acts as an oncogenic gene in glioblastoma multiforme cells, and higher ZYX expression promotes the metastasis of glioblastoma multiforme cells by regulating the transcription of STMN1." (PMID 37626810, 2023). "Several studies have shown that ZYX is upregulated in various cancers, including glioblastoma multiforme, colorectal cancer, oral squamous cell carcinoma and melanoma." (PMID 37547758, 2023). "This kind of synergism is also noted in this study in which combined inhibition of p110β/δ and JNK displayed synergistic inhibitory effects on glioblastoma cell proliferation and migration via blockade of Akt, zyxin and FAK activation." (PMID 27176481, 2016). "Recent studies have shown that the actin-interacting protein zyxin (ZYX), an LIM domain protein that translocates between the cytoplasm and nucleus, is a key oncogenic factor in glioblastoma and colorectal cancer." (PMID 37547758, 2023). "Glioblastoma cells treated with this drug combination showed reduced phosphorylation of Akt and ERK, and decreased protein expression of ROCK2 and Zyxin." (PMID 33407478, 2021). "Pharmacological inhibition of p110β or p110δ, but not p110α, displayed synergistic inhibitory effect with JNK inhibition on glioblastoma cell proliferation and migration through decreasing phosphorylation of Akt, FAK and zyxin, leading to blockade of lamellipodia and membrane ruffles formation." (PMID 27176481, 2016). "Thus, isoform-selective PI3K inhibitors impeded glioblastoma cell migration through blockade of FAK activation, and reduced FAK or zyxin activation contributed to the synergistic inhibitory effects on glioblastoma cell migration." (PMID 27176481, 2016). "The effect of disrupting netrin function on adhesive complex formation in glioblastoma cells was investigated by examining the distribution of paxillin, which is present in both FAs and FCs, and zyxin, which is present in FAs but not FCs." (PMID 21980448, 2011). "Inhibition of p110β or p110δ, but not p110α, exerted synergism with JNK on impeding glioblastoma cell proliferation and migration through decreasing Akt, focal adhesion kinase (FAK) and zyxin phosphorylation, resulting in the blockade of lamellipodia and membrane ruffles formation." (PMID 27176481, 2016).
melanoma (7 papers, 2015 to 2024). A malignant, usually aggressive tumor composed of atypical, neoplastic melanocytes. "Anti-PD-1 administration reduced the subcutaneous growth of melanoma-derived B16-F10 cells in Zyxin KO mice, with significantly more CD8+ T lymphocyte infiltration (Fig. EV6J)." (PMID 39304793, 2024). "We additionally examined the effect of neutralizing anti-PD-1 antibodies in Zyxin KO mice, which otherwise had a marginal effect on melanoma because of unfavorable tumor microenvironments." (PMID 39304793, 2024). "We also confirmed that combining Zyxin knockout with anti-PD-1 effectively reduced the growth of subcutaneously grown melanoma-derived cells in syngeneic murine models." (PMID 39304793, 2024). "Activation of STING-TBK1-Zyxin signaling was evident in B16-F10 melanoma (Fig. EV6A), and phospho-Zyxin induced upon cGAMP administration were mainly in F4/80+ macrophages and, to a lesser extent, in CD4+ T cells (Fig. EV6B,C)." (PMID 39304793, 2024). "Silencing WT1 resulted in decreased zyxin expression, leading to reduced proliferation of melanoma cells." (PMID 38712343, 2024). "Melanoma cells in which zyxin is upregulated were more spread while the spreading rate on fibronectin was reduced in epithelial cells where zyxin mislocalization was induced by a peptide inhibitor." (PMID 26509500, 2015). "To investigate whether the effects of STING-TBK1-Zyxin signaling were relied on IRF3, we inoculated B16-F10 melanoma cells into WT, Sting1−/−, Irf3−/−, or Zyxin−/−;Irf3−/− mice." (PMID 39304793, 2024). "In terms of promoting tumors, studies indicate that in melanoma cells, the expression of zyxin, focal adhesion kinase (FAK), and paxillin increases, directly correlating with cell spreading and proliferation but showing a negative correlation with differentiation." (PMID 38712343, 2024). "To investigate this possibility, we employed syngeneic models of B16-F10 melanoma and MC38 colon adenocarcinoma in Zyxin KO mice." (PMID 39304793, 2024).
colorectal cancer (6 papers, 2022 to 2026). A primary or metastatic malignant neoplasm that affects the colon or rectum. "ZYX encodes zyxin, a protein essential for cell focal adhesions, which is associated with increased motility, adhesiveness and metastatic potential in several tumor types, including hepatocellular and colorectal carcinomas." (PMID 41153808, 2025). "Increased levels of ZYX have been demonstrated in breast and colorectal cancers, while a suppressor role of this protein has been found in prostate and bladder cancers." (PMID 35740950, 2022). "Similarly, elevated zyxin levels have been reported in both colorectal cancer and hepatocellular carcinoma, where they contribute to cytoskeletal remodelling, cell migration, and proliferation." (PMID 41596291, 2026). "Zyxin (ZYX) is a LIM domain protein found in cytoplasm and nucleus, which has been shown to be involved in apoptosis, migration and invasion of cancer, and has potential as a prognostic marker for colorectal cancer 30697742." (PMID 38039294, 2023).
Ewing sarcoma (6 papers, 2007 to 2024). A small round cell tumor that lacks morphologic, immunohistochemical, and electron microscopic evidence of neuroectodermal differentiation. "This tumor suppressor role of zyxin was confirmed in a human Ewing tumor-derived cell line (SKNMC) which also produces low constitutive levels of zyxin." (PMID 32397195, 2020). "However, more research is needed to gain a deeper understanding of the specific mechanisms through which zyxin operates in Ewing sarcoma and its molecular events related to the occurrence and development of other tumors." (PMID 38712343, 2024). "In Ewing sarcoma, a downregulation of zyxin expression levels has been observed." (PMID 38712343, 2024). "The de-repression of ZYX might partially explain how NKX2-2 or EWS/FLI knockdown allows Ewing sarcoma cells to manifest mesenchymal characteristics." (PMID 26000096, 2015). "Interestingly, in Ewing tumour cells, zyxin is only expressed at very low levels and remains diffusely distributed throughout the cytoplasm instead of concentrating in actin-rich dynamic structures." (PMID 17211471, 2007).
bladder cancer (5 papers, 2019 to 2025). "The exact mechanism of zyxin in bladder cancer, though, requires further research for a detailed understanding." (PMID 38712343, 2024). "Zyxin also exhibits inhibitory effects on bladder cancer by influencing the β-catenin signaling pathway." (PMID 38712343, 2024). "Further, we find that both K14 and the focal adhesion protein, ZYX are required for bladder cancer migration and invasion." (PMID 38168254, 2023). "It has also been suggested that ZYX may act as a tumor suppressor protein in prostate and bladder cancers." (PMID 35740950, 2022).
colon cancer (5 papers, 2006 to 2023). "Our results suggested that zyxin and nesprin-1 are not only promising therapeutic targets but also potential diagnostic biomarkers for colon cancer." (PMID 31501460, 2019). "Our finding that ACTN1 and ACTN4 show differential affinities for ZYX may provide the molecular mechanism underlying the phenotypic outcome of ACTN overexpression in colon cancer cells." (PMID 25860875, 2015). "In this work, ELISA assays were performed using 20 sera samples from patients with colon cancer and 20 healthy donor samples to quantify the protein levels of zyxin and nesprin-1." (PMID 31501460, 2019). "Additionally, we performed ELISA assays on serum samples from patients with colon cancer instead of cell models to quantify the protein levels of zyxin and nesprin-1." (PMID 31501460, 2019). "Thus, elevation of ACTN4 protein expression and ancillary ZYX inhibition in colon cancer cells provides another mechanistic basis for cancer progression, while underscoring the importance of focal adhesion regulation in colon cancer." (PMID 25860875, 2015). "In two of these data sets, one or two genes had relatively high frequencies not noticeable with rules involving 20 or 50 genes: desmin for classifying colon cancer versus normal tissue; and zyxin and secretory granule proteoglycan genes for classifying two types of leukemia." (PMID 16959042, 2006).